MIR6799 (microRNA 6799)
Synonyms: hsa-mir-6799
Gene: MicroRNA gene on chromosome 19 (49,791,866 to 49,791,934, forward strand). Ensembl gene ENSG00000276270.
Homologues: Orthologues: chimpanzee MIR6799 (100% identical).